MTOR (mechanistic target of rapamycin kinase)
Diseases named in the same sentence as MTOR in open-access papers (continued):
Sharing a sentence is not in itself a finding about the gene and the disease.
colorectal cancer (continued). "RNA sequencing data suggests that NAT1 may regulate liver metastasis of colorectal cancer through the PI3K/AKT/mTOR signaling pathway and inhibits the expression of glycolytic-related metabolic enzymes such as GLUT1 and LDHA." (PMID 38916406, 2024). "MALAT1 could also upregulate FUT4 expression and enhances fucoidan glycosylation and in laboratory studies, MALAT1 triggers the activation of the PI3K/AKT/mTOR pathway, thereby promoting colorectal cancer cell invasiveness." (PMID 39830506, 2024). "ISL-NLs regulated AMPK/mTOR mediated glycolysis in colorectal cancer." (PMID 39444605, 2024). "Such mTOR blockade protects against chemotherapeutic agents in colorectal cancer and leukaemia; however, mechanisms linking mTOR inhibition to acquired chemoresistance remain unclear." (PMID 39080411, 2024). "Therefore, they proposed that APS can induce autophagy in colorectal cancer cells by inhibiting the PI3K/AKT/mTOR axis and the development of cancer cells." (PMID 38515577, 2024). "Previous studies have shown that elemene can induce apoptosis and autophagy in colorectal cancer cells through the ROS/MAPK/mTOR pathway, as well as regulate the epithelial-mesenchymal transition to inhibit the invasion and metastasis of colorectal cancer cells." (PMID 39765827, 2024). "Previous investigation elucidated that silibinin induced autophagy via enhancing AMP/ATP ratio, which transduced inhibitory signals to phosphatidylinositol‐4,5‐bisphosphate 3‐kinase catalytic subunit alpha‐protein kinase B–mammalian target of Rapamycin (mTOR) pathway in colorectal cancer cells." (PMID 38222315, 2024). "Additionally, it effectively suppresses the glycolysis ability and reduces VEGF expression in colorectal cancer cells by modulating the PI3K/AKT/mTOR signaling pathway." (PMID 38916406, 2024). "LETM1 controls the growth of CSCs in colorectal cancer (CRC) through ROS/AMPK/mTOR signaling." (PMID 39201332, 2024). "The apoptotic effect of NaB in colorectal carcinoma cells is mediated by the mTOR/S6K1 pathway." (PMID 39200243, 2024). "Fan could induce autophagy by activating the AMPK/mTOR/ULK1 signaling pathway in colorectal cancer cell lines." (PMID 37485535, 2023). "We next examined whether NaB is involved in mTOR- and ferroptosis-mediated colorectal cancer tumorigenesis in vivo." (PMID 37185889, 2023). "Therefore, HSF1 regulated DNMT3a/MIR137HG/MIR137 / GLS axis to raise glutaminolysis and mTOR activation and promote the process of colorectal cancer, and it is a potential therapeutic target for colorectal cancer." (PMID 37127605, 2023). "Furthermore, in colorectal cancer, in vitro and in vivo studies have shown the ability of MSC-conditioned media to upregulate NF-Kb signaling through the AMPK/mTOR pathway in colorectal cancer cells." (PMID 38002286, 2023). "In another study, lncRNA CKMT2-AS1 depressed the growth of colorectal cancer cells by targeting the AKT/mTOR pathway, which contradicts our data that lncRNA CKMT2-AS1 could be a poor indicator for pRCC rather than a protective factor." (PMID 36674979, 2023). "In contrast to our findings, SNX10 was reported to have a tumor suppressive effect in mouse inflammation-driven colorectal cancer models, with knockout leading to increased chaperone-mediated autophagy and mTOR activation and reduced autophagic degradation of SRC." (PMID 36795488, 2023). "The mTOR signaling pathway is a target for colorectal cancer therapy." (PMID 37651321, 2023). "The downregulation of MPC2 promotes glycolysis via the mTOR pathway in colorectal cancer cells." (PMID 37147584, 2023). "This miRNA is reported to suppress liver metastasis in colorectal cancer by downregulating mTOR." (PMID 36293349, 2022). "MYH9 may activate mTOR signaling in lung and colorectal cancers to induce cancer stem-like or chemo-resistant phenotypes." (PMID 36139430, 2022). "HOTAIR accelerates colorectal cancer progression via the PI3K/AKT/mTOR pathway." (PMID 35248107, 2022).
colorectal cancer (continued). "Therefore, we only performed knockdown KCNJ14 experiments in two cell lines of colorectal cancer and found that the levels of mTOR signalling pathway-related proteins decreased significantly." (PMID 36100894, 2022). "Current data have illustrated that glucose deficiency elevates the NBR2 profile in colorectal cancer cells, and NBR2 motivates curcumin to hamper colorectal cancer cells’ proliferation by stimulating adenosine monophosphate-activated protein kinase and choking the mTOR pathway." (PMID 35703318, 2022). "It has been discovered that mTOR signaling plays a significant role in colorectal cancer." (PMID 36293326, 2022). "Moreover, a previous study has shown that the depletion of PRMT5 significantly reduces the expression of phospho-ERK1/2 and phospho-mTOR in colorectal cancer cells." (PMID 33495409, 2021). "Additionally, the concentration of important proteins (sICAM-1, mTOR, Beclin-1, cathepsin B) involved in the pathogenesis and poor prognosis of colorectal cancer was also evaluated by ELISA." (PMID 33918514, 2021). "Experimental and preclinical studies have proven that mTOR is an effective target for colorectal cancer therapy, and considering the close correlation between QSOX2 and mTOR, QSOX2 also may provide promising perspectives for CRC therapy." (PMID 34858968, 2021). "The signaling pathways of Wnt, Yap, and mTOR play important roles in maintaining cancer stem cells in colorectal cancer, and it has recently been discovered that node signaling may also play a role." (PMID 34298652, 2021). "Among these mechanisms, the regulation of AMP-activated protein kinase (AMPK) and the mechanistic Target Of Rapamycin (mTOR) pathway in colorectal cancer cells (CRC) and the activation of endoplasmic reticulum (ER) stress response in melanoma and thyroid cancer have been described." (PMID 34204950, 2021). "Qi and colleagues reported that polysaccharides extracted from Cordyceps sinensis suppressed the formation of autophagolysosomes, resulting in a blockage of autophagy flux via the mammalian target of rapamycin (mTOR) signalling pathway in colorectal cancer (CRC) cells." (PMID 33669877, 2021). "Naringin promoted apoptosis of colorectal cancer by inhibiting the PI3K/AKT/mTOR signaling pathway." (PMID 34054546, 2021). "mTOR overactivity is mainly caused by the activation of the PI3K–Akt signaling pathway and occurs in virtually every type of tumor cell, including breast cancer cells, colorectal cancer cells, and gastric cancer cells." (PMID 34444753, 2021). "In fact, the IGF/mTOR/S6K1 signaling cascade plays an important role in colorectal carcinoma." (PMID 35010891, 2021). "Recent studies have shown that in mice with colitis and colorectal cancer, the activity of mTOR in inflammatory lesions and tumor lesions is enhanced, and the proliferation of intestinal epithelial cells in inflammatory lesions depends on the activity of mTOR." (PMID 32290362, 2020). "Therefore, the mechanisms relating detoxification by glutathione and miR-12/PI3K/AKT/mTOR, can be a useful tool in the diagnosis and treatment of colorectal cancer." (PMID 33381452, 2020). "The abnormal activation of the PI3K/AKT/mTOR signaling pathway has been observed in a variety of human tumors, including esophageal, ovarian, breast, and colorectal cancer and promoted the development of tumor by promoting cell proliferation, inhibiting apoptosis, or activating angiogenesis." (PMID 32454851, 2020). "It is expected that cotreatment of colorectal cancer cells with histone deacetylase inhibitors and indole-3-carbinol 70, would suppress histone deacetylase inhibitor-mediated apoptosis, as would rapamycin, given the importance of mTOR activity 71,72." (PMID 31942190, 2020). "However, as only one permanent CTC line was used in this study, the crucial role of the AKT/mTOR axis in colorectal cancer CTCs should be confirmed in the future when more long-term stable CRC CTC lines are available." (PMID 32962206, 2020).
colorectal cancer (continued). "Tian et al47 indicated that induction of autophagy regulated by Deptor/mTOR pathway might be a critical mechanism for glutamine limited the development of colorectal cancer related to olitis." (PMID 32510855, 2020). "The PI3K/AKT/mTOR axis plays a crucial role in colorectal carcinoma (CRC)." (PMID 32962206, 2020). "Protein levels in cancer cells, although many studies have reported a correlation between O‐GlcNAcylation and the mTOR pathway, the mechanism by which O‐GlcNAcylation regulates mTOR activation in colorectal cancer remains unclear." (PMID 30484950, 2019). "Similarly, we knocked down DDX5 on the basis of OGT overexpression or used the mTOR inhibitor (Rapamycin) significantly reduce the proliferation and metastasis of colorectal cancer cells." (PMID 30484950, 2019). "In summary, we propose to envision whether the OGT‐DDX5 axis regulates the proliferation and metastasis of colorectal cancer by activating the AKT/mTOR pathway." (PMID 30484950, 2019). "In addition, it has been reported that inhibition of the PI3K/Akt/mammalian target of rapamycin (mTOR) pathway by apigenin enhances Bax expression and suppresses Bcl-2 expression and tumor cell growth in cisplatin-resistant human colorectal cancer cells." (PMID 31769426, 2019). "In summary, we initially demonstrated that the regulation of colorectal cancer by the OGT‐DDX5 axis may be dependent on the AKT/mTOR signalling pathway." (PMID 30484950, 2019). "BA induces protective autophagy by inhibiting Akt/mTOR signaling in human colorectal cancer cells." (PMID 30850585, 2019). "Up-regulation of PI3K/Akt/mTOR is an important indicator for treatment with inhibitors of this pathway therefore an initial screen of phospho-Aktser473 and phosphor-mTORser2481 expression was carried out in 2 breast and 3 colorectal cancer cell lines." (PMID 30056610, 2019). "Additionally, Deptor, a suppressor of mTOR, has been demonstrated as a novel target of Wnt/β-catenin/c-Myc signaling pathway and contributes to the growth of colorectal cancer cell." (PMID 31431517, 2019). "A previous study has shown that both mTORC1 and mTORC2 regulate EMT, motility, and metastasis in colorectal cancer; therefore, the downregulation of mTOR induced by PtoxPdp may therefore affect EMT status." (PMID 31557166, 2019). "Thus, in the present study, we investigated the anticancer effect of TKSE against colorectal cancer and explored the molecular mechanisms responsible with focus on Akt/mTOR, ERK, and AMPK." (PMID 31624493, 2019). "Additionally, the expression of STAT3 and mTOR was analyzed in paired colorectal cancer and normal tissues collected from clinical patients." (PMID 31287013, 2019). "PI3K/Akt/mTOR/p70S6K, an important signaling pathway involved in cancer progression and metastasis, causes S100A4-promoted cell viability and migration, and promotes the VEGF secretion level through downregulation of E-cadherin in colorectal cancer cells." (PMID 30871059, 2019). "Our findings suggest that autophagic cell death via the CHOP/TRB3/Akt/mTOR pathway may represent a new mechanism of anti-colorectal cancer action by A. cinnamomea." (PMID 30479369, 2018). "mTOR is a serine/threonine protein kinase that regulates cell growth, cell proliferation, cell motility, cell survival, protein synthesis, and transcription and has been studied in colorectal cancer a potential therapeutic target." (PMID 28060954, 2017). "As to the role of PTRF in colorectal cancer progression, we found that ectopic expression of PTRF inhibited the activation of the AKT/mTOR pathway, suppressed proliferation, migration, and invasion, and reduced in vivo tumor growth of colorectal cancer cells with a relatively low PTRF expression." (PMID 27203393, 2017). "To further determine whether inhibition of the Akt/mTOR pathway is involved in TCO–induced autophagy, we activated the Akt/mTOR pathway by combinatorial treatment with insulin (Akt activator) in colorectal cancer cells." (PMID 28881770, 2017).
colorectal cancer (continued). "In a panel of human cancer cell lines of different histological origin, including isogenic colorectal cancer cell lines only differing for PTEN status, PTEN-loss effectively predicted synergistic growth inhibitory interactions between RAF/MEK and PI3K/AKT/mTOR inhibitors." (PMID 28220839, 2017). "Expression of experimentally mutated mTOR genes in cultured cells promotes tumorigenicity, and mutations to the genetic sequences of pathway components that modulate mTOR activity, such as PI3K, PTEN, and AKT have been detected in colorectal cancers." (PMID 27203393, 2017). "Other genes, such as nuclear factor kappa B1 (NFκB1), mammalian target of rapamycin (mTOR), and phosphatase tensin homolog deleted on chromosome 10 (PTEN), are major regulators of inflammation, are associated with colorectal cancer, and influence the TGF-B signaling pathway." (PMID 28061442, 2017). "Additional studies are needed to investigate whether LARP1 mediated cellular proliferation and prognosis of colorectal cancer by interacting with mTOR." (PMID 27614686, 2016). "Neuroendocrine tumors from small cell lung and colorectal cancers also display an enhanced sensitivity to mTOR pathway inhibition, indicating that the phenomenon may apply more broadly to other neuroendocrine cancers." (PMID 26776158, 2016). "The PI3K/Akt/mTOR signaling axis is critical in the proliferation, resistance to apoptosis, angiogenesis and metastasis, and is central to the development and maintenance of colorectal cancer cells." (PMID 25998232, 2015). "Increasing evidence has indicated that mTOR and its substrates are dysregulated in numerous human carcinomas and that mTOR knockdown by specific siRNAs could inhibit tumor growth in colorectal cancer." (PMID 25654224, 2015). "The results of the present study indicated that mTOR and pmTOR may be important in colorectal carcinoma and may present promising novel molecular targets for designing novel therapeutic strategies to control colorectalcarcinoma." (PMID 25120661, 2014). "Indeed, increased levels of phosphatidate have been linked to certain types of cancers through allosteric activation of the molecular target of rapamycin (mTOR) and to a possible role for lipin 2 in statin resistance of colorectal carcinoma cells in vitro." (PMID 25344859, 2014). "Our data confirm that the sensitivity of PIK3CA mutant colorectal cancer to PI3K/mTOR inhibitors may depend on the presence of wild-type KRAS gene." (PMID 23826249, 2013). "Also, silibinin inhibits PP2A/AKT/mTOR pathways and targets the inflammatory NF-kB pathways suppresses colorectal cancer stem like cells." (PMID 23530816, 2013). "We conclude that inducing apoptosis by TRAIL in combination with HSP90 or PI3 Kinase/mTOR inhibitors may represent a promising potential therapeutic approach for clinical evaluation in colorectal cancer." (PMID 23852390, 2013). "Based on these data, we hypothesized that inhibitors of PI3 Kinase/mTOR or HSP90 could enhance sensitivity to TRAIL in TRAIL-resistant colorectal cancer cells by modulating survival signaling." (PMID 23852390, 2013). "Interestingly, mTOR pathway was involved in the suppression of cell growth by COX-2 inhibitor in colorectal cancer, and the anti-angiogenic effect of mTOR inhibitor was in turn mediated by COX-2 in Ewing sarcoma." (PMID 22992293, 2012). "Other studies have shown that MSI colorectal cancer might be specifically sensitive to compounds inhibiting the phosphatidylinositol 3-kinase (PI3K)–AKT–mammalian target of rapamycin (mTOR) pathway." (PMID 22926706, 2012).
colorectal cancer (continued). "Using adiponectin-deficient mice (KO) we therefore investigated whether adiponectin deficiency might promote the development of colorectal cancer, and examined the involvement of the AMPK/mTOR pathway in the effect of adiponectin on colon carcinogenesis." (PMID 18676419, 2008). "Atractylon, at an appropriate concentration, can significantly inhibit the proliferation and promote the apoptosis of intestinal cancer cells via suppressing the PI3K/AKT/mTOR signaling pathway, which may be a potential candidate for the treatment of colorectal cancer and other related diseases." (PMID 38543015, 2024). "Therefore, miRNA-451-regulated activation of mTOR activity facilitates colorectal cancer progression and may be a potential target in the treatment of colorectal cancer." (PMID 38965615, 2024). "Moreover, in CRC cells, cystine/cysteine depletion triggers autophagy via the mTOR/ULK axis, indicating that combining cystine/cysteine depletion with mTOR or autophagy inhibitors may be a more successful treatment strategy for colorectal cancers." (PMID 39079386, 2024). "Besides, while mTOR inhibitors have been reported to suppress CSCs, other studies have demonstrated their ability to induce the expansion of drug-resistant CSCs, notably in breast and colorectal cancer." (PMID 37968262, 2023). "In addition, an analysis of colonic tissues using whole-transcriptome profiling revealed that enhanced PI3K-AKT-mTOR signaling in colorectal cancer mice was accompanied by a significant increase in the expression level of phosphorylated S6 ribosomal protein (a downstream target of the mTOR pathway)." (PMID 37511569, 2023). "Similarly, PDE4B was shown to modulate colorectal cancer growth through mTOR." (PMID 37427586, 2023). "The results indicated that MG7 caused cytotoxicity and apoptosis in colorectal cancer cells by mediated the expression of gene involved in cell cycle, apoptosis and necroptosis through key anticancer pathways such as NF-kappa B, Ras, MAPK, phosphatidylinositol, and mTOR." (PMID 36385303, 2022). "Moreover, one of the pathways that is upregulated in colorectal cancer is the mTOR pathway." (PMID 36080216, 2022). "However, little research has been performed to explore MTOR in colorectal cancer (CRC)." (PMID 35883111, 2022). "Moreover, FTO gene upregulation may play a role in colorectal carcinoma cells through phosphatidylinositol-3-kinase (PI3K)/Akt/mammalian target of rapamycin (mTOR) pathway." (PMID 36263301, 2022). "Furthermore, the Akt/mTOR signaling axis plays a crucial role in the proliferation, resistance to apoptosis, angiogenesis, and metastasis, and that is directed to the development and prolongation of colorectal cancer." (PMID 32566099, 2020). "For all subsections, it is uncertain whether colon microadenoma LT97 cells will be, to a greater or lesser extent, dependent upon the Wnt-Rb-mTOR pathway for histone deacetylase inhibitor-induced apoptosis than are colorectal cancer cells, including metastatic SW620 cells." (PMID 31942190, 2020). "Additionally, we could identify the inhibition of AKT and mTOR in CTCs as a novel druggable target in colorectal cancer." (PMID 32962206, 2020). "Additionally, rapamycin, which is an mTOR inhibitor, attenuates the EMT process and stem-like properties that are driven by FBXW7 loss, which indicates the pivotal role of the FBXW7/mTOR axis in EMT regulation in colorectal cancer." (PMID 30999935, 2019). "We determined whether the Akt/mTOR pathway was inhibited in TCO–treated colorectal cancer cells." (PMID 28881770, 2017). "However, whether PTRF directly depends on repressing the AKT/mTOR pathway in order to inhibit colorectal cancer progression remains to be determined." (PMID 27203393, 2017).